KDM5A (lysine demethylase 5A)
Diseases named in the same sentence as KDM5A in open-access papers (continued):
Sharing a sentence is not in itself a finding about the gene and the disease.
tumor (63 papers, 2010 to 2025). "High expression of KDM5A was significantly associated with poorer treatment efficacy (p = 0.037) and higher tumor grade (p = 0.019)." (PMID 35493099, 2022). "KDM5A was also found to be significantly associated with tumor stage progress and metastasis in patients with clear cell renal cell carcinoma." (PMID 33087165, 2020). "The encoded protein of KDM5A plays a role in gene regulation through the histone code by specifically demethylation lysine 4 of histone H3, many researchers thought this gene may play a role in tumor progression." (PMID 29026100, 2017). "In another example, KDM4A is recruited to H3K4me3-rich loci by KDM5A during DNA amplification events in tumours, with similar events occurring during maternal epigenetic inheritance in oocytes." (PMID 39062462, 2024). "In BC, KDM5 family members especially KDM5A/B are often overexpressed and promote tumor development by regulating cellular and molecular mechanisms." (PMID 38769556, 2024). "In line with this, NEAT1 was found to abrogate KDM5A expression via interacting with E2F1, which suppressed the KDM5A/H3K4me3-mediated repression of Cul4A expression, resulting in activated Wnt signaling pathway and augmented tumor formation." (PMID 39119602, 2024). "Our study validated FBXO22 as a tumor suppressor in TNBC through ubiquitination of KDM5A and regulation of p16." (PMID 36112263, 2023). "KDM5A cooperates with pRb25, a retinoblastoma tumor-suppressor protein and a regulator of muscle differentiation and development." (PMID 36509829, 2022). "In vivo studies using xenograft mouse models also show increased tumor sizes upon KDM5A overexpression." (PMID 36509829, 2022). "In other words, KDM5A plays an important role in both normal tissue protection and tumor suppression and is, therefore, a promising target for CP-induced ototoxicity." (PMID 36396833, 2022). "KDM5A increased the abundance of PD-L1 in tumor cells by suppressing the PTEN expression pathway and inducing PI3K-AKT-S6K signaling, and directly interacted with the Pten promoter (∼3 kb proximal to the transcription start site) to repress Pten transcription." (PMID 35051616, 2022). "Studies have shown that KDM5A increases the abundance of PD-L1 in tumor cells by inhibiting PTEN expression and inducing PI3K-AKT-S6K signal transduction." (PMID 35051616, 2022). "The high expression of KDM5A/B/C was related to poor clinical features, such as worse treatment efficacy, higher tumor grade, and more advanced clinical stage." (PMID 35493099, 2022). "Inhibition of KDM5A with small molecule inhibitors such as the pan-KDM inhibitor JIB 04 and the selective KDM5A inhibitor CP1445 efficiently inhibited tumor growth in vitro and in vivo of TMZ-resistant GBM." (PMID 34361090, 2021). "Further investigation will be necessary to provide evidence for a tumor suppressive function for KDM5A in CML." (PMID 34944554, 2021). "We carried out xenograft tumor experiments on the nude mice in order to verify the effect of KDM5A on PCa initiation and progression via the miR-495/YTHDF2/MOB3B axis in vivo." (PMID 33087165, 2020). "In summary, our study demonstrates that the overexpression of KDM5A has a tumor-supporting effect on PCa, as it suppresses the YTHDF2-dependent MOB3B expression by binding to miR-495." (PMID 33087165, 2020). "Compared to control shRNA animals, animals injected with KDM5A-depleted cells showed lower overall disease burden, and a reduction in primary tumor size (top)." (PMID 33196691, 2020). "On the other hand, nuclear KDM5A functions as a tumor suppressor by exerting its demethylase activity." (PMID 31776402, 2019). "KDM5A may exhibit dual roles as a tumor-promoting or tumor-suppressing agent in CRC in different microenvironments." (PMID 40699666, 2025). "Similarly, histone-modifying enzymes such as PRMT6 and KDM5A have emerged as important players in diverse cancer types, underscoring their roles in tumor metabolism and immune evasion." (PMID 40144021, 2025).
tumor (continued). "Overexpression of KDM2B and KDM5A genes plays significant roles in promoting poor differentiation and tumor proliferation in PDAC, respectively, whereas knockdown of the KDM3A gene leads to decreased invasive activities in culture and impedes the formation of orthotopic tumors in mice." (PMID 38791111, 2024). "Overexpression of Fbxo22 resulted in DNA damage in TNBC cells as indicated by a significant increase in γH2AX, and effectively slowed tumor invasiveness and metastasis both in vitro and in vivo, however, it was reversed upon simultaneous overexpression of Fbxo22 and KDM5A." (PMID 38769556, 2024). "Importantly, KDM5A are demonstrated to demethylase-dependently reduce tumor suppressor genes such as p27, p21, and p16." (PMID 36112263, 2023). "Furthermore, KDM5A depletion suppresses the growth of established tumors in pRb+/− mice, indicating that KDM5A is required not only for tumor formation but also for the maintenance of established tumors driven by pRb loss." (PMID 35805040, 2022). "KDM5A can directly or indirectly maintain tumor cell dryness, inhibit cell metabolism and differentiation, and promote the proliferation, metastasis, and drug resistance of tumor cells." (PMID 35126937, 2022). "In tumor cells, by removing H3K4me3, KDM5A inhibits multiple tumor suppressor genes involved in the cell cycle, invasion, epithelial–mesenchymal transition, and other processes that contribute to tumor progression." (PMID 36396833, 2022). "Scratch assay, transwell assay, Edu assay, pseudo‐tube formation assay and mice with xenografted tumours were conducted to investigate the physiological function of KDM5A‐miR‐433‐FXYD3‐PI3K‐AKT axis in the progression of HCC after loss‐ and gain‐function assays." (PMID 33621431, 2021). "Weights and sizes of tumors in the KDM5A-KO group were lighter and smaller than those in the WT group; thus, KDM5A knockout could suppress tumor growth in vivo." (PMID 33436536, 2021). "Subsequently, the expression of the cell division marker Ki67, indicative of tumor cell proliferation, was subjected to analysis whether the increase in KDM5A expression was related to tumor cell growth." (PMID 33436536, 2021). "KDM5A inhibition is therefore a logical therapeutic concept for RB−/− OS, as its inhibition would restore mitochondrial function, allow for differentiation, and ultimately diminish tumor cell proliferation." (PMID 29263893, 2016). "In addition to the ETV6-NTRK3 gene fusion, PGR, TERT, DOT1L, KDM5A and LRP1B mutations may be passenger mutations that promote tumor progression." (PMID 36585729, 2022). "KDM5A may function as a tumor suppressor by removing H3K4me3 on cell cycle-promoting genes." (PMID 36509829, 2022). "Furthermore, KDM5A has been shown to modulate tumor immunity." (PMID 35805040, 2022). "However, some studies also point out the tumor-suppressive roles of KDM5A in BC." (PMID 36509829, 2022). "For instance, KDM5A facilitates PCa progression by hyperactivating the PI3K/AKT signaling pathway, while KDM5B influences tumor metabolism and cell proliferation via epigenetic regulation." (PMID 40144021, 2025). "The top 5 overexpressed proteins in tumor compared to NT (ranked according to the log2(FC) T vs CT) included SFRP2, KDM5A, CMTM5, HSPA5 and FN1." (PMID 39681068, 2024). "For instance, KDM5A is known to be overexpressed in GBM cell lines resistant to TMZ, and the knockout of this gene efficiently downregulates tumor proliferation in vivo and in vitro in these resistant cells in addition to increasing their sensitivity to TMZ." (PMID 36425564, 2022). "Using the xenograft tumor model in vivo, they found that knockdown of KDM5A and PHF2 not only reduced the tumor burden in the primary tumor but also induced a more pronounced decrease in metastatic disease burden." (PMID 36230825, 2022).
tumor (continued). "KDM5A is also a prognostic indicator for RCC, and it promotes EMT to induce stemness in tumor cells." (PMID 33596982, 2021). "KDM5A is a kind of jumonji domain-containing demethylase for H3K4ME3, and it has been reported to act as a molecular oxygen sensor in the tumor cells." (PMID 33499904, 2021). "We detected the presence of miR‐433, FXYD3, p‐AKT and p‐p85 expressions in tumour tissues, which demonstrated that KDM5A silencing led to significant increase in miR‐433 and reduction in expression levels of FXYD3, p‐AKT and p‐p85 in tumour tissues (P < .05)." (PMID 33621431, 2021). "Because RB inactivation is so prominent and potent in OS tumor cells, RB-related therapeutics such as CDK inhibitors, KDM5A inhibitors and Hh agonists deserve the spotlight in the field of OS research." (PMID 29263893, 2016). "Therefore, AKT/RICTOR-mediated phosphorylation of DNMT1 and/or KDM5A regulates gene expression, including that of UGCG, leading to an increase in glucosylceramides and enhanced tumor progression." (PMID 40934285, 2025). "Furthermore, to assess the protein expression levels of KDM1A, KDM5A, and KDM5B in human tumor tissue, we conducted IHC on a tumor tissue microarray." (PMID 39239542, 2024). "Most evidence supports that KDM5A/B is a carcinogenic factor in BC, while KDM5C may have tumor suppressive functions." (PMID 38769556, 2024). "While KDM6A and KDM6B have a tumor suppressor role, other members of the KDM family like KDM2B, KDM3A, and KDM5A may serve as oncogenes in PDAC." (PMID 38791111, 2024). "Notably, KDM5A has been shown to interact with the HDAC complex, thereby influencing tumor chemosensitivity." (PMID 37880235, 2023). "In addition, KDM5A mediates reduction in methylated H3K4 and thus decreases the levels of two tumor suppression and differentiation genes KLF4 and E-cadherin, which lead to the malignancy of PCa." (PMID 33596982, 2021). "Therefore, KDM5A silencing significantly suppresses HCC tumorigenesis in vivo, accompanied with down‐regulated miR‐433 and up‐regulated FXYD3‐PI3K‐AKT axis in tumour tissues." (PMID 33621431, 2021). "Furthermore, KDM5A was found to downregulate MOB3B expression, consequently augmenting PCa cell proliferation, migration and invasion in vitro and promoting tumor growth in vivo via the miR-495/YTHDF2 axis." (PMID 33087165, 2020). "Therefore, we were interested in investigating whether KDM1A, KDM5A, and KDM5B expression was correlated with the enrichment of tumor-infiltrating lymphocytes in PC." (PMID 39239542, 2024). "KDM5A and KDM5B have been indicated to be carcinogenic in numerous studies, while KDM5C and KDM5D may function as tumor suppressors, although the evidence is conflicting which may be due to the specific tumor microenvironment and different experimental conditions." (PMID 38769556, 2024).
neurodevelopmental disorder (2 papers, 2020 to 2024). A behavioral and cognitive disorder with onset during the developmental period that involves impaired or aberrant development of intellectual, motor, or social functions. "Prior to our study, it was not known whether KDM5A loss-of-function mutations result in ASD or in other neurodevelopmental disorders." (PMID 33350388, 2020). "The fact that mutations in KDM5A, KDM5B, and KDM5C all cause neurodevelopmental disorders, indicates that their function in the brain is nonredundant." (PMID 33350388, 2020).
adenocarcinoma (1 paper, 2011). A common cancer characterized by the presence of malignant glandular cells. "Hypoxia has also been shown to play a role in KDM5A (JARID1A) activity in the lung bronchial epithelial cell line Beas-2B and NSCLC adenocarcinoma cell line A549." (PMID 24212667, 2011).
heart disease (1 paper, 2020). "For example, while CDK13, CHD4, KDM5A, and SCN10A are related to familial heart disease, CFH, DGUOK, and POLE are related to familial vascular disease." (PMID 31941532, 2020).
hematologic malignancies (1 paper, 2025). "These comprise master transcription factors of the leukemogenic program of NUP98::KDM5A-driven AML, as well as other genes which have not been associated with hematologic malignancies." (PMID 40389480, 2025).
kidney diseases (1 paper, 2024). "Among them were several genes known to be involved in kidney diseases, such as Kdm5a, Rb1, Tead1, Xbp1 and Ppargc1α with so far unknown role as sexual dimorphism regulators." (PMID 39278930, 2024).
metabolic disorders (1 paper, 2025). "Together, the study reveals the regulatory mechanisms of KDM5A in age-dependent metabolic disorders and identifies KDM5A/FABP4 axis as a potential therapeutic target for vascular aging and related organ dysfunction." (PMID 41236095, 2025).
psychiatric disease (1 paper, 2021). "Further, Pou6f2, Kdm5a, Reep3, Wdfy3 have been implicated in psychiatric diseases such as autism and Pigr was found to be involved in response to psychological stress." (PMID 34285244, 2021).
KDM5A also shares sentences with these, for which no sentence is quoted: hepatocellular carcinoma (7 papers); colorectal cancer (3); ankylosing spondylitis (2); bladder cancer (2); breast invasive carcinoma (2); endometrial cancer (2); renal cell carcinoma (2); adrenocortical carcinoma (1); Alzheimer disease (1); angiosarcoma (1); arrhythmogenic right ventricular cardiomyopathy (1); atherosclerosis (1); autoimmune disease (1); autoimmune thyroid disease (1); B-cell lymphoma (1); chronic pancreatitis (1); Cirrhosis (1); Cognitive impairment (1); colon cancer (1); degenerative disease (1); developmental delay (1); diabetic nephropathy (1); epilepsy (1); erythroleukemia (1); estrogen-receptor negative breast cancer (1); gastric adenocarcinoma (1); glomus tumor (1); hepatocellular adenoma (1); infection (1); Insulin resistance (1).
A further 22 diseases each share a sentence with KDM5A in 1 paper.